MAGIX (MAGI family member, X-linked)
Synonyms: PDZX; JM10; FLJ21687
Tractability: PROTAC: its protein half-life has been measured.
Gene: Protein-coding gene on chromosome X (49,162,564 to 49,168,774, forward strand). Ensembl gene ENSG00000269313.
Subcellular location (Human Protein Atlas): Nucleoplasm; Mitotic chromosome
Homologues: Orthologues: chimpanzee MAGIX (99% identical), macaque MAGIX (87% identical), pig MAGIX (72% identical), mouse Magix (63% identical), rat Magix (62% identical), rabbit MAGIX (55% identical), Caenorhabditis elegans magi-1 (22% identical), zebrafish magixb (22% identical), zebrafish magixa (21% identical), Drosophila melanogaster Magi (19% identical). Paralogues in human: MAGI2 (30% identical), MAGI3 (30% identical), MAGI1 (30% identical), GRIP2 (19% identical), GRIP1 (16% identical), SAV1 (7% identical).
Diseases named in the same sentence as MAGIX in open-access papers:
MAGIX is named in the same sentence as 1 disease in open-access papers, as found by Europe PMC text mining. Sharing a sentence is not in itself a finding about the gene and the disease. The quoted sentences say what the papers report.
thyroid cancer (1 paper, 2020). "The Human Protein Atlas indicates that MAGIX mRNA is moderately expressed in liver, gastric, pancreatic, and thyroid cancers." (PMID 32869486, 2020).